ABCA6 (ATP binding cassette subfamily A member 6)
Description:
Probable transporter which may play a role in macrophage lipid transport and homeostasis.
Synonyms: EST155051
Tractability: Antibody: its Gene Ontology location is reachable by antibodies, with high confidence; UniProt predicts a signal peptide or a membrane-spanning region. PROTAC: ubiquitination databases record sites on it; its protein half-life has been measured.
Gene: Protein-coding gene on chromosome 17 (69,074,255 to 69,142,031, reverse strand). Ensembl gene ENSG00000154262.
Subcellular location: Golgi apparatus membrane
Subcellular location (Human Protein Atlas): Nucleoplasm
Pathways (Reactome):
Gene expression (Transcription): FOXO-mediated transcription of oxidative stress, metabolic and neuronal genes
Transport of small molecules: ABC transporters in lipid homeostasis
Gene Ontology:
Molecular function: ATPase-coupled transmembrane transporter activity; ABC-type transporter activity; ATP binding; ATP hydrolysis activity
Biological process: transmembrane transport
Cellular component: Golgi membrane; nucleoplasm; plasma membrane; membrane
Genetic constraint (gnomAD): Loss-of-function variants: 110 observed, 123.78 expected, observed/expected ratio (o/e) 0.89, 90% interval 0.76 to 1.04. The upper end of that interval is the gene's LOEUF score, 1.04, which puts it in group 4 of 6, group 1 being the genes least tolerant of losing a copy. Missense variants: 1,470 observed, 1,435.9 expected, observed/expected ratio (o/e) 1.02, 90% interval 0.98 to 1.07. Synonymous variants: 483 observed, 501.01 expected, observed/expected ratio (o/e) 0.96, 90% interval 0.89 to 1.04.
Homologues: Orthologues: chimpanzee ABCA6 (99% identical), macaque ABCA6 (96% identical), rabbit ABCA6 (77% identical), pig ABCA6 (77% identical), dog ABCA6 (75% identical), rat Abca6 (68% identical), mouse Abca6 (68% identical), guinea pig ABCA6 (66% identical), zebrafish abca5 (40% identical), Caenorhabditis elegans abt-4 (23% identical), Drosophila melanogaster Abca3 (23% identical), Caenorhabditis elegans abt-2 (23% identical), and 10 more. Paralogues in human: ABCA8 (59% identical), ABCA10 (59% identical), ABCA9 (59% identical), ABCA5 (41% identical), ABCA1 (27% identical), ABCA4 (26% identical), ABCA7 (26% identical), ABCA13 (25% identical), ABCA3 (25% identical), ABCA12 (25% identical), ABCA2 (25% identical).
Diseases named in the same sentence as ABCA6 in open-access papers:
ABCA6 is named in the same sentence as 25 diseases in open-access papers, as found by Europe PMC text mining. Sharing a sentence is not in itself a finding about the gene and the disease. The quoted sentences say what the papers report.
breast carcinoma (3 papers, 2020 to 2025). "Conversely, genes on chromosome 17 region “Nikolsky Breast Cancer 17q21-q25” were amplified in CR and contained ATP-binding cassette (ABC) transporters (ABCA5/ABCA6/ABCA8/ABCA9/ABCA10) among them (172 genes total, FDR = 7.39E−178)." (PMID 37012431, 2023). "The role of the ATP-binding cassette (ABC) transporters in tumorigenesis of White breast cancer patients is further supported by the enrichment of the “brown” module in basal transcription factors, including the ATP-binding cassette subfamily members ABCA9, ABCC9, ABCG2, ABCB1, ABCA6, and ABCA8." (PMID 32873298, 2020).
gastric cancer (2 papers, 2023 to 2025). A primary or metastatic malignant neoplasm involving the stomach. "Leveraging the Cancer Genome Atlas (TCGA) dataset, we stratified gastric cancer patients into N0–N3 categories and identified a core set of molecules, including ABCA6, DCLK1, and ADCYAP1, whose expression is tightly linked to LN metastasis." (PMID 41049174, 2025). "We found that molecules such as ABCA6, DCLK1, and ADCYAP1 were linked to higher risk, with DCLK1 and ADCYAP1 being downregulated, while THPO and C5orf46 were upregulated in gastric cancer tissues." (PMID 41049174, 2025).
lymphoma (2 papers, 2014 to 2022). A malignant (clonal) proliferation of B- lymphocytes or T- lymphocytes which involves the lymph nodes, bone marrow and/or extranodal sites. "In the present GWAS meta-analysis, there was suggestive evidence that inherited polymorphisms in the ABCA10 or ABCA6 genes may be associated with risk of lymphoma-specific death." (PMID 25294155, 2014). "Additionally, publicly available data showed that ABCA6 was expressed at lower levels in EWS compared with other pediatric tumors, particularly lymphoma/leukemia, suggesting the lack of this transporter as a peculiar feature of EWS." (PMID 36149602, 2022).
pancreatic cancer (2 papers, 2025). "Members of the ABCB, ABCC, and ABCG families are well-established mediators of therapy resistance, and recent studies have also implicated ABCA6 and ABCA8 in drug resistance in pancreatic cancer." (PMID 41515995, 2025). "Emerging evidence supports a role for the ABCA subfamily in chemoresistance, with GH upregulating ABCA6 and ABCA8 in pancreatic cancer." (PMID 40806252, 2025).
bone metastasis (1 paper, 2020). Transfer of a neoplasm from its primary site to bones. "More importantly, among the OS-SEs, we identified two bone metastasis-related ASEs (ABCA6-43162-AT and PLIN5-46808-AT) co-expressing with SF YBX3 and pathway of primary bile acid biosynthesis." (PMID 32627826, 2020).
hepatocellular carcinoma (1 paper, 2022). A malignant tumor that arises from hepatocytes. "ABCA6 is related to the survival time of patients with hepatocellular carcinoma, but its relationship with the prognosis of GC is unclear." (PMID 35912206, 2022).
liver cancer (1 paper, 2020). An epithelial or non-epithelial malignant neoplasm that arises from the liver. "At the cellular level, YBX3 and CH25H were highly expressed in liver cancer cell lines, and ABCA6, PLIN5, AMACR, AKR1D1, CYP27A1, CYP46A1 were highly expressed in liver cancer cell lines in CCLE." (PMID 32627826, 2020).
Obesity (1 paper, 2024). Accumulation of substantial excess body fat. "The expression of PTX3, NCF2, HOXB5, ABCA6, and C1orf162 were upregulated in the placenta of mothers with obesity compared with mothers with normal BMI." (PMID 39296904, 2024). "However, the role of ABCA6 in obesity has never been reported before." (PMID 39296904, 2024).
prostatic tumor (1 paper, 2015). "In addition to ABCA11, the extra-prostatic tumor stage (pT3 vs pT2) was associated with the down-regulation of other ABC transporter genes from subfamily A: ABCA5 (FC 1.73; p = 0.022), ABCA6 (FC 2.00; p = 0.046), and ABCA10 (FC 3.29; p = 0.006)." (PMID 26459268, 2015).
tumor (9 papers, 2020 to 2025). "In the ω-3 group, GPR120 WT BMD M2-like macrophages infiltrating the tumor were significantly reduced in number and gene expression of cholesterol transporters Abca1, Abca6, and Abcg1." (PMID 37872251, 2024). "Accordingly, tumor-related death occurred in 30.4% (7 out of 23) of patients with high expression of ABCA6, but in 69.6% (16 out of 23) of patients with low expression of the transporter (p = 0.046, Fisher’s exact test)." (PMID 36149602, 2022). "Conversely, proteins of interest in tumor-bearing rats elevated following OKN-007 treatment included ABCA6, ADAMTS18, VWA8, MACF1, and LAMA5." (PMID 35053843, 2022). "Our study reveals that ABCA6 acts as tumor suppressor in EWS cells via cholesterol-mediated inhibition of IGF1R/AKT/MDM2 signaling, which promotes the pro-apoptotic effects of doxorubicin and reduces cell migration." (PMID 36149602, 2022). "In our current study, we found that high tumor levels of ABCA6 were predictive of a favorable prognosis in EWS patients." (PMID 36149602, 2022). "Conversely, proteins of interest in tumor-bearing rats that were elevated following OKN-007 treatment included ABCA6, ADAMTS18, VWA8, MACF1, and LAMA5." (PMID 35053843, 2022). "Although some members of the superfamily of ATP-binding cassette transporters play important roles in tumor-generating mechanisms and drug resistance, the specific biological role of ABCA6 is not clearly understood." (PMID 32299435, 2020). "Our previous studies have identified ABCA6, ABCC6 and ABCG5 as potential tumor-suppressor genes in HCC." (PMID 35280774, 2022). "Furthermore, we measured the expression of ABCA6, ABCC6, and ABCG5 in 50 pairs of early-stage tumor tissues and paratumor tissues using quantitative reverse transcription polymerase chain reaction (qRT-PCR)." (PMID 35280774, 2022).
cancer (5 papers, 2022 to 2025). A tumor composed of atypical neoplastic, often pleomorphic cells that invade other tissues. "The expression of ABCA6 can impair intracellular levels of cholesterol, which is important for regulating the membrane fluidity of cancer cells." (PMID 39575432, 2024). "Emerging data suggests that cancer cells secrete factors that activate cholesterol transporters in macrophages such as ABCA1 ABCA6 and ABCG1 to increase cholesterol efflux." (PMID 37872251, 2024). "Overall, our study highlights the importance of ABCA6 in cancer and provides a mechanistic explanation for its involvement in the regulation of cancer aggressiveness." (PMID 36149602, 2022). "Our findings highlight the importance of ABCA6 as a biomarker of risk and response in EWS and provide a mechanistic explanation for its involvement in the regulation of cancer aggressiveness." (PMID 36149602, 2022).
infection (1 paper, 2020). The state of being infected such as from the introduction of a foreign agent such as serum, vaccine, antigenic substance or organism. "Of interest, the least ABCA1 and ACAT1 proteins in BCG-infected bovine AMs were observed at post infection 6 h, while the ABCG1 was at 12 h, and the least ABCA5 and ABCA6 were at 24 h post infection." (PMID 32397995, 2020). "Accordingly, the least ABCG1, ABCA1 and ACAT1 proteins in BCG-infected RAW264.7 cells were found at 12 h post infection, while the least ABCA5 and ABCA6 were at 24 h post infection." (PMID 32397995, 2020).
ABCA6 also shares sentences with these, for which no sentence is quoted: acute myeloid leukemia (1 paper); B-cell lymphomas (1); brain tumors (1); dislocation (1); epilepsy (1); Ewing sarcoma (1); gingival hyperplasia (1); Harlequin ichthyosis (1); keratoconus (1); leukemia (1); neuroblastoma (1); osteoarthritis (1); Patellar dislocation (1).